GDF15 (growth differentiation factor 15)
Diseases named in the same sentence as GDF15 in open-access papers (continued):
Sharing a sentence is not in itself a finding about the gene and the disease.
gastric tumors (3 papers, 2021 to 2023). "In head and neck, breast, and gastric tumors, a high expression of GDF15 by cancer stem cells contributes to maintaining their properties." (PMID 38201456, 2023). "Whereas, in the case of GDF15 mRNA in gastric tumors and protein levels in peripheral blood of GC patients, the data converge and present increased levels of GDF15 in patients with GC in comparison to the healthy population." (PMID 34149933, 2021). "Likewise, the analysis of the TCGA dataset also confirmed that GDF15 overexpression was most common in G1-G2 gastric tumors." (PMID 34149933, 2021). "Although there is no clear consensus about the GDF15 expression level in gastric tumors compared to normal gastric tissues, most scientific reports have indicated a higher level of this protein in tumors than in normal tissues 40, 41, which is also consistent with our results." (PMID 34149933, 2021). "However neither GRFAL expression nor especially the joint expression of GDF15, GFRAL and RET have been evaluated in gastric tumors, in the context of the potential implication of the body-weight signaling pathway in GC pathogenesis." (PMID 34149933, 2021).
Hyperinsulinemia (3 papers, 2021 to 2024). An increased concentration of insulin in the blood. "In the patient group we studied, elevated GDF-15 plasma levels were associated with reactive hyperinsulinemia." (PMID 39456699, 2024). "Elevated GDF-15 levels were found in 12 patients; all of them had a BMI > 25 kg/m2, which is associated with reactive hyperinsulinemia." (PMID 39456699, 2024). "Hyperinsulinemia increases circulatory GDF-15 during different stages of adiposity." (PMID 33874963, 2021).
inclusion body myositis (3 papers, 2022 to 2025). A slowly progressive degenerative inflammatory disorder of skeletal muscles characterized by late onset weakness of specific muscles and distinctive histopathological features. "Moreover, GDF-15 levels are higher in individuals with idiopathic inflammatory myopathies, including conditions such as inclusion body myositis, PM and DM, and are associated with serious complications such as myocardial injury." (PMID 38058222, 2025).
Infertility (3 papers, 2024). "Only a few studies have evaluated the relationship between androgens, infertility, and GDF-15 levels." (PMID 39420932, 2024). "Additionally, GDF-15 levels appeared to be involved in biologic pathways related to inflammation, glucose metabolism, adipogenesis, and infertility, which are pathways also involved in the pathophysiology of PCOS." (PMID 39420932, 2024). "Finally, GDF-15 is involved in biologic pathways related to inflammation, glucose metabolism, adipogenesis, and infertility, all of which are related to PCOS complications." (PMID 39420932, 2024).
juvenile dermatomyositis (3 papers, 2023 to 2025). Juvenile dermatomyositis (JDM) is the early-onset form of dermatomyositis (DM), a systemic, autoimmune inflammatory muscle disorder, characterized by proximal muscle weakness, evocative skin lesion, and systemic manifestations. "Similarly, in juvenile dermatomyositis, GDF-15 levels strongly correlate with disease activity scores and functional measures, making it a valuable biomarker for evaluating disease activity and guiding treatment decisions." (PMID 39328401, 2024).
lipodystrophy (3 papers, 2020 to 2024). A congenital or acquired disorder characterized by abnormal loss or redistribution of the adipose tissue in the body. "(2020) observed increased GDF-15 levels in mice with lipodystrophy, which decreased after treatment with leptin." (PMID 39420932, 2024). "This reinforces the hypothesis that leptin and GDF-15 act through independent pathways in humans, which is consistent with a study in patients with lipodystrophy and hypoleptinemia, wherein leptin treatment failed to normalize GDF-15 levels." (PMID 38890300, 2024).
lupus nephritis (3 papers, 2024 to 2025). Glomerulonephritis in the context of systemic lupus erythematosus. "For instance, Macedo and colleagues identified a positive relationship between GDF-15 and serum creatinine in individuals with lupus nephritis." (PMID 40722837, 2025).
lymphoma (3 papers, 2015 to 2023). A malignant (clonal) proliferation of B- lymphocytes or T- lymphocytes which involves the lymph nodes, bone marrow and/or extranodal sites. "Mean plasma endostatin and GDF15 levels were significantly higher in symptomatic and asymptomatic lymphoma patients than in controls." (PMID 37223632, 2023). "Boxplots visualizing levels of GDF15, endostatin, MMP9, and NGAL in ng per mL, in controls and in patients with asymptomatic and symptomatic lymphoma." (PMID 37223632, 2023).
malaria (3 papers, 2016 to 2025). Malaria is a serious and sometimes fatal disease caused by a parasite that commonly infects a certain type of mosquito which feeds on humans. "Identified studies examined GDF15 in malaria, and tuberculosis, as well as the studies involving children with HIV described in the mitochondrial section above." (PMID 40019842, 2025). "However, children with symptomatic malaria had increased GDF15 levels." (PMID 40019842, 2025).
MERRF (3 papers, 2020 to 2022). A mitochondrial encephalomyopathy characterized clinically by a mixed seizure disorder, myoclonus, progressive ataxia, spasticity, and a mild myopathy. "Concordantly, two chemokines related to the mtUPR and the mitochondrial integrated stress response (mtISR), FGF21 and GDF-15, have been found increased in serum samples from MERRF patients." (PMID 35922766, 2022). "Cell free circulating-mtDNA (ccf-mtDNA), a new biomarker for mitochondrial diseases, and GDF15 levels were significantly increased in patients with mitochondrial encephalomyopathy lactic acidosis stroke-like episodes syndrome (MELAS) and myoclonic epilepsy ragged red fibers (MERRF) syndrome." (PMID 34445593, 2021).
metastatic prostate carcinoma (3 papers, 2016 to 2019). A carcinoma that arises from the prostate gland and has spread to other anatomic sites. "Elevated serum levels of GDF15 have been found in metastatic prostate cancer patients and is strongly associated with poor clinical outcome." (PMID 28883652, 2017). "While elevated serum levels of GDF15 has been associated with metastatic prostate cancer and poor clinical outcome, it remains unclear whether GDF15 was associated with early stage invasion." (PMID 28883652, 2017).
mitochondrial encephalomyopathy (3 papers, 2020 to 2024). A heterogenous group of disorders characterized by alterations of mitochondrial metabolism that result in muscle and nervous system dysfunction. "Genetic sequencing is the gold standard for diagnosing mitochondrial encephalomyopathies, preceded by non-invasive tests such as fibroblast growth factor-21 and growth differentiation factor-15." (PMID 38391710, 2024).
mood disorder (3 papers, 2015 to 2023). A cognitive disorder a disturbance in which the person's mood is hypothesized to be the main underlying feature. "Recently, elevated serum GDF15 level was proposed as a marker for mood disorder." (PMID 28801589, 2017).
mucositis (3 papers, 2023 to 2026). Mucositis is inflammation and damage of the mucous membranes lining the mouth and other parts of the gastrointestinal (GI) tract. "We examined the effects of Gdf15 deficiency on CP-induced mucositis in mice." (PMID 37270567, 2023). "GDF15 was not correlated with any adverse events, including leukopenia, neutropenia, increased creatinine, anorexia, nausea, or mucositis oral and pathological response." (PMID 41016991, 2026).
obstructive sleep apnea syndrome (3 papers, 2015 to 2024). Cessation of air flow during sleep due to upper airway obstruction. "GDF-15 level was not studied in patients with obstructive sleep apnea syndrome (OSAS) before." (PMID 26075263, 2015).
overnutrition (3 papers, 2020 to 2024). An imbalanced nutritional status resulting from excessive intake of nutrients. "It was shown that while short-term overnutrition did not increase GDF15, longer periods of caloric excess increased circulating GDF15 levels." (PMID 39768899, 2024). "Similarly to GDF15, circulating FGF21 has also been shown to be largely derived from the liver in obese HFD fed mice raising the question of why two stress responsive hormones are secreted in this context of overnutrition." (PMID 36064109, 2022).
pancreatic adenocarcinoma (3 papers, 2020 to 2025). "Pancreatic adenocarcinoma study also revealed that the activation of NF-κB directly regulates the MIC-1/GDF15 expression in tumor development." (PMID 33081054, 2020).
pancreatitis (3 papers, 2015 to 2024). Inflammation of the pancreas. "In PC, GDF-15 testing had an AUC of 0.82 for its ability to differentiate PC from pancreatitis, which was higher than its ability to distinguish PC from healthy individuals." (PMID 30808336, 2019). "Moreover, GDF-15 had an AUC of 0.82 for its ability to distinguish PC from pancreatitis, which was a higher value than the AUC for its ability to distinguish PC from healthy individuals (AUC = 0.73)." (PMID 30808336, 2019).
polyp (3 papers, 2012 to 2020). A usually exophytic mass attached to the underlying tissue by a broad base or a thin stalk. "For MIC-1/GDF15, the only other study in transgenic cancer models, have been in the APCmin/+ small and large bowel polyp prone mice." (PMID 22952779, 2012). "In patients from the polyp prevention trial, a higher polyp free serum MIC-1/GDF15 level afforded protection from polyp recurrence and NSAID mediated protection was lost if MIC-1/GDF15 serum levels were not elevated with NSAID treatment." (PMID 25695521, 2015).
prostate adenocarcinoma (3 papers, 2020 to 2023). "Next, we examined GDF15 expression in a PCa tissue microarray (TMA), which showed higher staining of GDF15 in prostate adenocarcinoma than in normal prostate samples and increased expression with disease progression." (PMID 35058441, 2022). "In keeping with an antitumorigenic action of GDF15, GDF15 knockout increases mortality, tumor number, and tumor size in a mouse model of spontaneous prostate adenocarcinoma." (PMID 32310257, 2020).
pseudoexfoliative glaucoma (3 papers, 2020 to 2024). "Importantly, elevated AH GDF15 has also been shown to correlate with disease severity (based on the median deviation of visual field loss) in POAG and pseudoexfoliation glaucoma patients." (PMID 35160195, 2022). "Previous studies have reported significant elevations in AH and serum levels of GDF15 protein in small cohorts of POAG and pseudoexfoliation glaucoma patients, where the increased levels of AH GDF15 exhibited a positive correlation with disease severity." (PMID 35160195, 2022).
renal cell carcinoma (3 papers, 2019 to 2025). "Another cancer type in which GDF-15 has been associated with a more favorable outcome is renal cell carcinoma (RCC)." (PMID 39000420, 2024). "Another study revealed that individuals diagnosed with renal cell carcinoma (RCC) exhibited elevated levels of serum GDF15 compared to the control group." (PMID 40854626, 2025). "Likewise, patients with renal cell carcinoma (RCC) and increased GDF-15 protein levels in tumor tissue show a better outcome." (PMID 39000420, 2024). "In the current retrospective analysis, the role of serum hepcidin and GDF-15 as prognostic markers in upper urinary tract urothelial carcinomas (UUTUC) and renal cell carcinoma (RCC) were investigated." (PMID 30646851, 2019). "In this study, the potential of serum hepcidin and serum GDF-15 as biomarkers that correlate with patient’s survival in the two entities upper urinary tract urothelial carcinomas (UUTUC) and renal cell carcinoma (RCC) were analyzed." (PMID 30646851, 2019).
respiratory failure (3 papers, 2019 to 2025). The significant impairment of gas exchange within the lungs resulting in hypoxia, hypercarbia, or both, to the extent that organ tissue perfusion is severely compromised. "This may be due to whole‐body metabolic changes driven by mTORC1 activation, respiratory failure secondary to compromised respiratory muscles, or other incompletely evaluated phenotypes of accelerated aging associated with mTORC1 and/or GDF15." (PMID 30924297, 2019). "In a pilot study of 142 patients recovering from acute respiratory failure, circulating GDF‐15 levels correlated with poor muscle outcomes." (PMID 40842041, 2025).
scleroderma (3 papers, 2011 to 2025). Scleroderma is a rare autoimmune connective tissue disorder characterized by abnormal hardening of the skin and, sometimes, other organs. "A recent study identified expression of GDF-15 protein in pulmonary macrophages of patients with PAH due to scleroderma, but almost no GDF-15 staining in IPAH lungs." (PMID 21548946, 2011).
Splenomegaly (3 papers, 2019 to 2022). Abnormal increased size of the spleen. "When hepcidin, GDF15 and mitoferrin-1 levels were analyzed according to the presence of JAK2 mutation and splenomegaly, it was found that hepcidin levels were significantly lower in the patients with JAK2 mutation (P = 0.007)." (PMID 30761871, 2019). "Relationships between hepcidin, GDF15, and mitoferrin-1 levels and presence of JAK2 mutation and splenomegaly." (PMID 30761871, 2019). "Erythropoietic expansion as evidenced by the respective markers like soluble transferrin receptors (sTfR), increased nucleated red cells (NRBCs) and growth differentiation factor 15 (GDF-15), will also contribute to splenomegaly leading many clinicians to recommend splenectomy." (PMID 33072976, 2019).
subarachnoid hemorrhage (3 papers, 2021 to 2024). A serious neurological disorder characterized by intracranial hemorrhage into the subarachnoid space. "However, a recently published observational trial also linked higher GDF-15 levels with incidental intracerebral and subarachnoid hemorrhage in the general population, independently of other known risk factors." (PMID 35455481, 2022). "One study showed that serum GDF15 was elevated in patients following subarachnoid haemorrhage, and this elevation in the first 9 days related to worsened primary and secondary neurological outcomes at 90 day follow up." (PMID 39737171, 2024).
systolic heart failure (3 papers, 2022 to 2024). Heart failure caused by abnormal myocardial contraction during systole leading to defective cardiac emptying. "Blockade of GDF15 could constitute a novel therapeutic option to limit cardiac cachexia and improve clinical outcomes in patients with severe systolic heart failure." (PMID 39312445, 2024). "Blockade of GDF15 could constitute a novel therapeutic option to limit cardiac cachexia and improve cardiac function and clinical outcomes in patients with severe systolic heart failure." (PMID 39312445, 2024).
uremia (3 papers, 2021 to 2026). A clinical syndrome associated with the retention of renal waste products or uremic toxins in the blood. "The relationship between the expression of GDF-15 in mice and HT22 brain cells under conditions of increased uremia was investigated to determine whether uremic toxins were associated with an increase in brain GDF-15 levels." (PMID 38397960, 2024). "In HD patients, exposure to multiple inflammatory agents, cardiac problems, and uremia might all be related to increased cellular stress, resulting in activation of GDF-15 and the nutrition axis." (PMID 34247467, 2021).
uveal melanoma (3 papers, 2020 to 2022). A melanoma derived from melanocytes of the uveal tract. "Blood-based B-cell activating factor (BAFF), growth differentiation factor-15 (GDF-15) and osteopontin (OPN) have been reported to be biomarkers for the uveal melanoma (UM) metastases." (PMID 34070192, 2021). "Blood-based B-cell activating factor (BAFF), growth differentiation factor-15 (GDF-15) and osteopontin (OPN) have been identified to be promising biomarkers for the metastases of uveal melanoma (UM)." (PMID 34070192, 2021).
viral hepatitis (3 papers, 2011 to 2026). An acute or chronic inflammation of the liver parenchyma caused by viruses. "In conclusion, these results suggest that an elevated serum GDF15 level is a potential diagnostic marker for viral hepatitis, and GDF15 may contribute to HCV pathogenesis by altering the signaling and growth of host cells." (PMID 21625435, 2011). "To date, no prospective studies have assessed the predictive value of GDF15 in HCC detection or its role in non-viral hepatitis related HCC." (PMID 34638361, 2021). "Therefore, we propose that GDF15 represents a potential biomarker and interventional target for hepatitis C or B. A further large-scale association study is urgently needed for the predictive significance of GDF15 in viral hepatitis." (PMID 21625435, 2011). "Across aetiologies, median GDF‐15 levels were highest in patients with ALD (3420 pg/mL) and lowest in patients with viral hepatitis (1640 pg/mL; p < 0.001)." (PMID 41555670, 2026). "In the context of HCC, comparison of serum GDF15 levels in a Chinese cohort of 223 HCC cases, predominantly due to viral hepatitis, showed elevated levels in sera of HCC patients as compared to HBV/HCV controls." (PMID 34638361, 2021). "However, an association between GDF15 and viral hepatitis has not been reported, so far." (PMID 21625435, 2011).
Addison’s disease (2 papers, 2020 to 2026). "We observed significantly higher levels of GDF15 in the Addison’s disease cohort who were glucocorticoid deficient than in the matched healthy volunteer cohort 739.1 ± 225.8 pg/mL versus 497.9 ± 167.7 pg/mL (P = .01), respectively." (PMID 31853550, 2020). "GDF15 levels are increased in glucocorticoid deficiency; however, multiple factors may influence its levels in patients with primary adrenal insufficiency (PAI)." (PMID 41828483, 2026). "To evaluate the reproducibility of the observation that glucocorticoid replacement in PAI was associated with a reduction in circulating GDF15 we assessed 2 independent PAI cohorts comprising of patients with Addison’s disease (cohort 2) or classical CAH (cohort 3)." (PMID 31853550, 2020). "The effect of hydrocortisone replacement on GDF15 was assessed in 3 independent PAI cohorts with classical congenital adrenal hyperplasia or Addison’s disease; intravenous hydrocortisone replacement reduced GDF15 in all groups." (PMID 31853550, 2020). "We measured circulating concentrations of GDF15 in a cohort of healthy volunteers and Addison’s disease patients following steroid withdrawal." (PMID 31853550, 2020). "Patients with Addison’s disease had their glucocorticoid and mineralocorticoid therapy withdrawn for at least 39 hours (see methods—placebo group cohort 1) prior to measurement of morning cortisol and GDF15." (PMID 31853550, 2020).
amyloidosis (2 papers, 2025). A disorder characterized by the localized or diffuse accumulation of amyloid protein in various anatomic sites. "Plasma GDF‐15 levels in patients with late‐onset transthyretin amyloidosis were higher than in patients with early‐onset amyloidosis." (PMID 39781722, 2025). "GDF‐15 levels differed in patients with the different transthyretin genotypes of amyloidosis." (PMID 39781722, 2025).
aneurysm (2 papers, 2021). Bulging or ballooning in an area of an artery secondary to arterial wall weakening. "Most importantly, our findings suggest the potential usefulness of the circulating levels of IgG, CD38 and GDF15 to assist AAA management in conjunction with aneurysm diameter and/or PWS during the follow-up of these patients." (PMID 33919749, 2021).